ENSG00000200051
Synonyms: LOC124901194
Gene: Small nucleolar RNA gene on chromosome 5 (140,527,352 to 140,527,428, reverse strand). Ensembl gene ENSG00000200051.
Gene Ontology:
Biological process: RNA processing
Cellular component: nucleolus
Homologues: Orthologues: mouse Snord45c (92% identical), rat Snord45c (91% identical). Paralogues in human: SNORD45C (94% identical), SNORD45A (82% identical), SNORD45B (77% identical).